UBTF (upstream binding transcription factor)
Diseases named in the same sentence as UBTF in open-access papers (continued):
Sharing a sentence is not in itself a finding about the gene and the disease.
Alzheimer disease (1 paper, 2024). A progressive, neurodegenerative disease characterized by loss of function and death of nerve cells in several areas of the brain leading to loss of cognitive function such as memory and language. "Evidently, changes in UBTF expression are found in some neurologic disorders including Alzheimer’s disease (AD) and Parkinson’s disease." (PMID 38391753, 2024).
breast invasive carcinoma (1 paper, 2026). "CRISPR-Cas9-mediated UBTF depletion was conducted in breast invasive carcinoma (BRCA) cell lines to evaluate functional roles." (PMID 41898767, 2026).
cerebral infarction (1 paper, 2023). An ischemic condition of the brain, producing a persistent focal neurological deficit in the area of distribution of the cerebral arteries. "Combination of the results of complete upstream pathway analyses suggests that transcription factors and protein kinases, such as UBTF and MAPK1, may be involved in the reduction of cerebral infarction volume after FNS." (PMID 37525090, 2023).
Childhood-Onset Neurodegeneration with Brain Atrophy (1 paper, 2024). "Recently, a recurrent de novo dominant mutation in UBTF (c.628G>A, p.Glu210Lys; UBTF E210K) was identified as the cause of a neurological disorder which has been named UBTF Neuroregression Syndrome (UNS), or Childhood-Onset Neurodegeneration with Brain Atrophy (CONDBA)." (PMID 38391753, 2024).
COVID-19 (1 paper, 2022). A disease caused by infection with severe acute respiratory syndrome coronavirus 2. "In the present study, four risk regulators (UBTF, POLR2L, YBX1 and YPEL2) were identified to be associated with COVID-19 severity." (PMID 35139909, 2022).
depression (1 paper, 2020). "Therefore, Wfs1/UBTF/mmu-mir-17-5 may play an important role in the pathogenesis of depression caused by long-term stress." (PMID 33552119, 2020). "These were then integrated into the network and the TF-microRNA core regulatory network was built, from which key microRNAs (mmu-mir-17-5p and mmu-mir-7b-5p) and TF (UBTF) in depression can be identified." (PMID 33552119, 2020). "Screening by qRT-PCR found that the expression of UBTF in the CUMS group was upregulated compared to the control group, suggesting a correlation in the pathogenesis of depression." (PMID 33552119, 2020).
developmental delay (1 paper, 2022). "Here, we report a CONDBA‐like proband with a unique, presumed de novo, missense UBTF variant, p.(Gln203Arg), who has additional, distinct phenotypic features of early‐life developmental delay and multiple neuroimaging abnormalities." (PMID 36106513, 2022).
erythroleukemia (1 paper, 2023). Acute erythroid leukemia characterised by the presence of at least 50% erythroid precursors and at least 20% myeloblasts in the bone marrow. "Interestingly, a recent comprehensive molecular study of erythroleukemia patients reported 3 patients with 6 bp-deletions in UBTF, similar to those which we observed in our cohort." (PMID 37236968, 2023).
metastatic melanoma (1 paper, 2021). A melanoma that has spread from its primary site to another anatomic site. "The UBTF expression was also remarkable higher in metastatic melanoma tissues than in tumor and normal skin tissues (p < 0.001)." (PMID 34663332, 2021).
myelodysplastic syndrome (1 paper, 2023). A clonal hematopoietic disorder characterized by dysplasia and ineffective hematopoiesis in one or more of the hematopoietic cell lines. "Due to limited knowledge on UBTF-TDs in adult AML, we screened 4247 newly diagnosed adult AML and higher-risk myelodysplastic syndrome (MDS) patients using high-resolution fragment analysis." (PMID 37236968, 2023).
ovarian carcinoma (1 paper, 2024). A malignant neoplasm originating from the surface ovarian epithelium. "Incorporating the somatic mutations in non-coding regions revealed a slightly broader spectrum of findings, of which potentially significant discoveries include UBTF in Ovarian Cancer (OV) and ACTBL2 in HNSC." (PMID 38241355, 2024).
cancer (19 papers, 2013 to 2026). A tumor composed of atypical neoplastic, often pleomorphic cells that invade other tissues. "On the other hand, upstream binding transcription factor (UBTF), a member of the HMG-box DNA-binding protein family and an integral part of ribosome biogenesis, has been linked to the advancement and chemoresistance in cancer." (PMID 39410048, 2024). "Owing to its detrimental role in actively proliferating cancer cells, various studies have speculated that targeting UBTF might become a promising therapeutic strategy in the management of cancer." (PMID 39410048, 2024). "Little is known about the involvement of UBTF in cancer progression." (PMID 36231068, 2022). "SOX2, UBTF, NFE2L2, TCF3 and STAT3 were underlined as common transcriptional factors, which are responsible for the upregulation of genes involved in processes of the epithelial–mesenchymal transition, cancer stemness, invasion and migration of GBM." (PMID 36231068, 2022). "It has been found that UBTF involves in carcinogenesis and progression of a few cancers." (PMID 34663332, 2021). "Interestingly, both RAB34 and UBTF were recently found to be involved in cancer development." (PMID 37689310, 2023). "Nevertheless, the function of UBTF in other cancers is still unknown." (PMID 34663332, 2021). "Thus, developing tools to target rDNA chromatin regulatory factors (such as UBTF) might provide a therapeutic window in certain cancers." (PMID 30701204, 2019). "We integrated datasets from The Cancer Genome Atlas (TCGA), Genotype-Tissue Expression (GTEx), Human Protein Atlas (HPA), Cancer Cell Line Encyclopedia (CCLE), and cBioPortal databases to characterize UBTF expression, genomic alterations, and prognostic value across 33 cancer types." (PMID 41898767, 2026). "To date, no natural pharmacological inhibitor has been developed for the effective and selective targeting of ribosome biogenesis components, including UBTF and RPA194, along with RPs, to treat cancer due to their nucleolar localization and other unfavorable surface attributes." (PMID 39410048, 2024). "The notably high overlapping ratios were discerned for TFs playing critical roles in transcription pre-initiation or RNA polymerase activities, e.g., UBTF, TAF1, and POLR2A, in addition to others, like E2F6, IRF1, and MYC, which are involved in cancer-related processes." (PMID 36092921, 2022). "The function of UBTF in cancers has not been extensively studied." (PMID 34663332, 2021).
tumor (9 papers, 2015 to 2026). "UBTF represents a pancancer biomarker linked to tumor immunity, with validated functional significance in BRCA and potential utility for risk stratification." (PMID 41898767, 2026). "Co-immunoprecipitation (CO-IP) analysis further confirmed the physical interaction between RPF2 and UBTF at the cell line and tumor tissue levels." (PMID 40917497, 2025). "Silencing UBTF suppressed cell multiplication, cell cycle progression and tumor growth, and promoted apoptosis." (PMID 34663332, 2021). "The data of tumor size and weight revealed that tumor growth was evidently restrained by UBTF shRNA as compared with that seen in sh-Ctrl group." (PMID 34663332, 2021). "Next, sh-Ctrl-infected and UBTF shRNA-infected A375 cells were injected subcutaneously and tumor growth was observed." (PMID 34663332, 2021). "Recently, studies found that UBTF involved in oncogenesis and development in a few tumor." (PMID 34663332, 2021). "In this study, we suggested that RPF2 overexpression could enhance the catalytic activity of RNA pol I via strengthening the expression and binding activity of UBTF, thereby up-regulating rRNAs production and ribosome formation, ultimately promoting tumor proliferation and invasion." (PMID 40917497, 2025). "In contrast, genes such as PTGES3 and UBTF exhibited significant negative correlations, suggesting tumor-cell-intrinsic functions." (PMID 40299459, 2025).
infection (3 papers, 2009 to 2022). The state of being infected such as from the introduction of a foreign agent such as serum, vaccine, antigenic substance or organism. "By confocal microscopy, we confirmed that endogenous IFI16 and UBTF colocalize in fibroblasts during mock infection and early HSV-1 infection." (PMID 31337724, 2019).
neurodegenerative disease (3 papers, 2020 to 2023). A disorder of the central nervous system characterized by gradual and progressive loss of neural tissue and neurologic function. "A new childhood-onset neurodegenerative disease affecting ribosomal metabolism has been shown to be associated with a monogenic UBTF (Upstream Binding Transcription Factor) (NM_014233.3) c.628G>A (p.Glu210Lys) gene variant." (PMID 36138999, 2022). "A new monogenic neurodegenerative disease affecting ribosomal metabolism has recently been identified in association with a monoallelic UBTF putative gain of function variant (NM_001076683.1:c.628G>A, hg19)." (PMID 31931739, 2020).
neurological diseases (2 papers, 2023 to 2024). "The UBTF E210K neuroregression syndrome is a predominantly neurological disorder caused by recurrent de novo dominant variants in Upstream Binding Factor, that is, essential for transcription of the ribosomal RNA genes." (PMID 37600660, 2023). "Other deleterious UBTF variants have been described in patients with neurological disease and reported in clinical-genetic databases (ClinGen and ClinVar)." (PMID 37600660, 2023). "This suggests that UBTF plays an important role in normal brain function and that changes in its expression can contribute to the symptoms of neurological diseases." (PMID 38391753, 2024).
UBTF also shares sentences with these, for which no sentence is quoted: hepatocellular carcinoma (3 papers); systemic sclerosis (3); autoimmune disorder (2); cervical carcinoma (2); liver cancer (2); scleroderma (2); acute erythroid leukemia (1); acute megakaryoblastic leukemia (1); adenovirus infection (1); B-cell precursor acute lymphoblastic leukemia (1); Cockayne syndrome (1); generalized epilepsy (1); glioblastoma (1); head and neck squamous cell carcinoma (1); Huntington disease (1); lymph node metastasis (1); lymphoma (1); mastitis (1); myositis (1); Neurodegeneration (1); Neurodevelopmental delay (1); osteosarcoma (1); pancreatic cancer (1); Parkinson disease (1); poliovirus infection (1); Promyelocytic Leukemia (1); stomach cancer (1); systemic lupus erythematosus (1); viral infections (1).